ANO5 (anoctamin 5)
Diseases named in the same sentence as ANO5 in open-access papers (continued):
Sharing a sentence is not in itself a finding about the gene and the disease.
intestinal disease (1 paper, 2019). "In another example, ANO5 transcription was positively correlated with abundance of Enterobacter as well as Shigella, both Enterobacteriaceae associated with human intestinal disease." (PMID 31552140, 2019).
ANO5 also shares sentences with these, for which no sentence is quoted: Scott syndrome (3 papers); cardiomyopathy (2); sarcoglycanopathies (2); thrombosis (2); Areflexia (1); autosomal recessive spinocerebellar ataxia (1); breast carcinoma (1); calpainopathies (1); cardiovascular diseases (1); cholesteryl ester storage disease (1); common variable immunodeficiency (1); congenital heart disease (1); congenital long-QT syndrome (1); coronary artery disease (1); dermatomyositis (1); Duchenne muscular dystrophy (1); Dystonia (1); hyperuricemia (1); hypokalemic periodic paralysis (1); muscular disorder (1); musculoskeletal disorders (1); Myalgia (1); neurodevelopmental disorder (1); neuromuscular disease (1); osteogenesis imperfecta (1); osteomyelitis (1); ovarian carcinoma (1); Pompe disease (1); respiratory failure (1); rhabdomyolysis (1).
A further 2 diseases each share a sentence with ANO5 in 1 paper.